LINC01483 (long independently transcribed non-coding RNA 1483)
Gene: Long non-coding RNA gene on chromosome 17 (69,563,386 to 69,903,566, forward strand). Ensembl gene ENSG00000227517.
Diseases named in the same sentence as LINC01483 in open-access papers:
LINC01483 is named in the same sentence as 1 disease in open-access papers, as found by Europe PMC text mining. Sharing a sentence is not in itself a finding about the gene and the disease. The quoted sentences say what the papers report.
breast carcinoma (1 paper, 2018). "In summary, we report three novel MD loci at genome-wide significance, of which HABP2 and LINC01483 may represent putative new breast cancer susceptibility loci." (PMID 29665850, 2018). "Of the newly identified loci, two (HABP2 and LINC01483) showed associations with MD that are consistent with the MD-breast cancer risk association, suggesting that part of their effect on breast cancer susceptibility is mediated through a directionally consistent change in MD." (PMID 29665850, 2018). "In this study, we identified three novel MD loci at genome-wide significance (percent dense volume [HABP2] and absolute dense volume [INHBB, LINC01483]), of which two (HABP2, LINC01483) represent putative novel breast cancer susceptibility variants." (PMID 29665850, 2018).